SERPINE2 (serpin family E member 2)
Diseases named in the same sentence as SERPINE2 in open-access papers (continued):
Sharing a sentence is not in itself a finding about the gene and the disease.
tumor (continued). "Fn was found to significantly enhance the expression of Serpine2 in fibroblasts and to promote the proliferation and migration capabilities of tumor cells." (PMID 40642075, 2025). "In fact, Serpine2 can contribute to tumor metastasis by enhancing the permeability of extravascular matrix and promoting the formation of vascular-like network structures in epithelial cells was reported in Nature." (PMID 40642075, 2025). "The current explorations of SERPINE2 are insufficient to fully illustrate the diversity of its involvement in tumor development." (PMID 40463876, 2025). "co-expression network analysis, KEGG and GO analysis revealed that SERPINE2 expression correlates with tumor immunoregulation, division and proliferation." (PMID 40463876, 2025). "As a secreted protein, we intended to explore the impact of SERPINE2 on the tumor immune microenvironment." (PMID 40463876, 2025). "Subsequently, we performed IHC staining analysis of VM-related markers, including VM markers VE-cadherin, Fibronectin 1 (FN1), SERPINE2, tumor microenvironment markers MMP2 and MMP9, epithelial cell marker E-cadherin and mesenchymal cell marker vimentin." (PMID 38164156, 2024). "Our in vitro studies suggest that LDL is potentiating intravasation through a VM-like mechanism, as LDL promotes the intercalation of tumor cells with endothelial cells in both 2D and 3D cell culture conditions and the expression of SERPINE2." (PMID 38658568, 2024). "We classified the cohorts according to the clinical information and found that SERPINE2 expression was significantly higher in the tissues with metastasis (p = 0.038) and a higher Fuhrman grade (p = 0.0091) or tumor stage (p = 0.0076) based on the IHC score." (PMID 36646679, 2023). "SERPINE2 has been reported to participate in metastasis of several human cancers through various mechanisms, such as by re-establishing tumor stroma and the polarization of TAM, or activation of glycogen synthesis kinase 3β and P38 pathways." (PMID 36646679, 2023). "YTHDF2 inhibits tumor cells and the tumor vascular system by regulating interleukin-11 (IL-11) and SERPINE2 mRNAs." (PMID 38072944, 2023). "We discovered that the expression of SERPINE1 and SERPINE2 were significantly related to tumor stage in COAD." (PMID 38274096, 2023). "Nevertheless, the current explorations of SERPINE2 cannot fully illustrate the diversity of its involvement in tumor development." (PMID 36797769, 2023). "H-score quantitative analysis showed that the expression of SERPINE2 in tumor tissue group was higher than that in para-tumor tissue group (p = 0.001)." (PMID 36646679, 2023). "For example, the expression level of SERPINE2 was positively correlated with the level of CD4 T cells infiltration in the tumor, and it is well-known that CD4 T cells can enhance antitumor activity of cytotoxic T lymphocytes." (PMID 37468850, 2023). "Nevertheless, the current explorations of SERPINE2 cannot fully illustrate the diversity of its involvement in tumor development, especially, the function of circRNAs arising from SERPINE2 has not been fully elucidated." (PMID 36797769, 2023). "Metastasis is an important cause of poor prognosis of HB, and a large number of previous studies have reported that SERPINE2 is closely related to tumor invasion and metastasis." (PMID 36505099, 2022). "SERPINE2 affects tumor invasion and migration through regulation of matrix metalloproteinases and plasminase systems." (PMID 36505099, 2022). "SERPINE2 promotes HB tumor progression by inhibiting apoptosis and promoting migration and invasion of HB cells." (PMID 36505099, 2022). "The qRT-PCR results showed that SERPINE2 mRNA expression level in tumor tissues was significantly higher than that in the corresponding liver tissues." (PMID 36505099, 2022). "In summary, LHX2 is significantly upregulated in ESCC tissues and promotes ESCC tumor growth and metastasis by augmenting the expression of SERPINE2." (PMID 36011368, 2022).
tumor (continued). "The high expression of SERPINE2 was closely related to tumor size (P = 0.021), vascular invasion (P = 0.029), tumor metastasis (P = 0.039), and PRETEXT stage (P = 0.049)." (PMID 36505099, 2022). "Serpin family E member 2 (SERPINE2) is overexpressed in a variety of tumors, especially adenocarcinoma, and promotes tumor invasion and metastasis." (PMID 36505099, 2022). "The high expression of SERPINE2 was related to tumor size, vascular invasion, tumor metastasis, and PRETEXT stage." (PMID 36505099, 2022). "Significant and marginal associations between increased SERPINE2 immunoexpression and high tumor grade have also been noted for UTUC and UBUC, respectively; higher SERPINE2 immunoexpression was associated with worse OS and DFS." (PMID 34679626, 2021). "YTHDF2 inhibits inflammasome-mediated tumor vascularization and malignancy by degradation of m6A-containing serpin family E member 2 (SERPINE2) and interleukin-11 (IL-11) mRNA." (PMID 33692959, 2021). "SERPINE2 knockdown has been proven to inhibite tumor cell invasion and metastasis, indicating that SERPINE2 likewise can serve as a potential therapeutic target." (PMID 32850407, 2020). "SERPINE2 belongs to a family of Serpins that inhibit the activity of serine protease and promote tumor metastasis and progression." (PMID 33324561, 2020). "The expression level of BAP31 was positively associated with the expression levels of SERPINE2, its downstream gene LRP1, and tumor cell proliferation marker Ki-67." (PMID 33363167, 2020). "Among these genes, SERPINE2 was expressed at high levels both in AcCC tumor samples and NCI-H292 cells after overexpression of both NR4A3 and Myb." (PMID 32867110, 2020). "Despite the sensitivity of destabilizing IL11 and SERPINE2 mRNAs in response to tumor hypoxia, YTHDF2 expression is readily silenced in the presence of active HIF-2α." (PMID 31735169, 2019). "From 4 weeks after injection, the tumour volume in circ‐SERPINE2 silence group was markedly smaller than that in the control." (PMID 31199037, 2019). "The extracellular serine protease inhibitor serpinE2, also named protease nexin-1 (PN-1), contributes to enhanced metastasis of cancer cells mainly by remodeling the tumor matrix." (PMID 31501409, 2019). "In this context, we unexpectedly found that YTHDF2 resisted either tumor angiogenesis or vascular mimicry by targeting SERPINE2." (PMID 31735169, 2019). "Taken together, these results show that Ab11 binds to serpinE2 and to serpinE2/protease complexes produced in vitro in the extracellular milieu of rodent and human tumor cell lines." (PMID 27793045, 2016). "Our results suggest that serpinE2 is required in the extracellular milieu of tumors to regulate tumor matrix deposition, thereby controlling tumor cell dissemination." (PMID 27793045, 2016). "In summary, our findings suggest that serpinE2 is required in the extracellular milieu of tumors where it acts in multiple ways to regulate tumor matrix deposition, thereby controlling tumor cell dissemination." (PMID 27793045, 2016). "Treatment with Ab11 resulted in no change in matrix density, clearly showing the importance of tumor-produced serpinE2 in the phenotype." (PMID 27793045, 2016). "It was recently shown that 4T1 tumor cells with elevated serpinE2 intravasated more efficiently than controls, which is in accord with the data shown here and our previous publication." (PMID 27793045, 2016). "Previous studies have demonstrated the potential role of SERPINE2 in tumor metastasis." (PMID 40463876, 2025). "Moreover, the mechanisms by which Fn regulates Serpine2 and influences the tumor microenvironment remain insufficiently explored." (PMID 40642075, 2025). "Serpin family E member 2 (SERPINE2) released from the tumor microenvironment exhibits significant regulatory functions in cancer progression but the role of SERPINE2 in the tumor microenvironment remains unclear." (PMID 40463876, 2025).
tumor (continued). "Additionally, the mRNA levels of Serpine2 in tumor tissues from metastatic patients were significantly greater than those in paired normal colon tissue samples." (PMID 40642075, 2025). "SerpinE2 also functions as a key factor in tumor dissemination, but the molecular mechanism by which this protease inhibitor governs cell migration and metastasis is largely unknown." (PMID 38634469, 2024). "In HCC, BAP31 promotes tumor growth via interaction with SERPINE2 and may act as a potential therapeutic target." (PMID 37296105, 2023). "The trend of elevated SERPINE2 expression in tumor tissues was observed in COAD and PAAD." (PMID 38274096, 2023). "SERPINE1 and SERPINE2 expression significantly increased in tumor advanced stage in COAD." (PMID 38274096, 2023). "Recent studies have reported that SERPINE2 is overexpressed in a variety of tumors and promotes tumor progression, and SERPINE2 may be an oncogenic gene." (PMID 36505099, 2022). "Moreover, the SERPINE2 expression was related to tumor size, vascular invasion, and tumor metastasis." (PMID 36505099, 2022). "In view of the correlation between the expression level of SERPINE2 and tumor invasion and metastasis, we speculate that the expression level of SERPINE2 is also correlated with the survival and prognosis of patients." (PMID 36505099, 2022). "In view of the correlation between the expression level of SERPINE2 and tumor invasion and metastasis, we speculated that SERPINE2 might be involved in epithelial-mesenchymal transition." (PMID 36505099, 2022). "Our study found that the expression level of SERPINE2 in HB tumor tissues was significantly higher than that in adjacent tissues, suggesting that SERPINE2 may be the oncogenic gene of HB." (PMID 36505099, 2022). "Taken together, these findings suggest that LHX2 may enhance tumor growth and metastasis by transcriptionally upregulating the SERPINE2 expression in ESCC." (PMID 36011368, 2022). "Moreover, due to their anticoagulant properties, Serpine2 and Slpi seemed to promote both the passage of erythrocytes into the tumor as well as that of cancer cells into the bloodstream." (PMID 34359928, 2021). "A recent study on UBUC demonstrated that SERPINE2 might play important roles in activating and recruiting immune cells, which can significantly impact tumor behavior regulation and treatment response." (PMID 34679626, 2021). "These genes included SERPINE2, which is actively involved in tumor cell proliferation and invasion." (PMID 33363167, 2020). "Moreover, multiplex immunohistochemistry staining of the HCC tissue microarray showed positive associations between the expression levels of BAP31, SERPINE2, its downstream gene LRP1, and a tumor proliferation marker, Ki-67." (PMID 33363167, 2020). "Circ‐SERPINE2 knockdown inhibited tumour growth of GC via regulation miR‐375/YWHAZ in vivo." (PMID 31199037, 2019). "Thus, our findings that circ‐SERPINE2 was upregulated and promoted tumour development in GC would conductive to uncover the complex function in area of circRNAs." (PMID 31199037, 2019). "We speculate that these biochemical and cellular changes all contribute to the deposition of a dense extracellular collagen I matrix, encapsulating the serpinE2-blocked tumors, which inhibits intravasation and tumor spread." (PMID 27793045, 2016). "4T1 tumor cells secrete serpinE2 and multiple target proteases." (PMID 27793045, 2016). "Here, we investigated the hypothesis that serpinE2 creates tumor-promoting conditions in the tumor microenvironment (TME) by affecting extracellular matrix remodeling." (PMID 27793045, 2016). "Decreasing serpinE2 levels led to elevated Hh pathway activity and ensuing increased tumor growth." (PMID 27793045, 2016). "Therefore, the present analysis reveals an aberrant role for Serpine2/PN-1 in tumor growth and malignant progression, which likely complements its previously established functions in tumor invasion and metastasis." (PMID 25901736, 2015).
tumor (continued). "Overall, our in vitro data suggest that high LDL potentiates the ability of tumor cells to intercalate and transmigrate endothelial cell monolayers in a way that resembles VM/mosaic vessel formation and may involve the increased expression of SERPINE2." (PMID 38658568, 2024). "Chromatin loop analysis identified 4,168 HB-specific and 4,009 non-tumor-specific chromatin interactions, anchoring 187 DEGs, including TRIB2, SERPINE2, and MYCN." (PMID 41462308, 2025). "Our prognostic signature include four genes, SERPINE2, SNCAIP, NMU, and S100A9, each playing a critical role in tumor progression, invasion, and metastasis." (PMID 37691944, 2023). "However, the molecular mechanisms by which SERPINE2 enhances tumor metastasis remains unclear." (PMID 36646679, 2023). "SERPINE2 was highly expressed in RCC tissues and lowly expressed in para-tumor tissues or HK-2 cell line." (PMID 36646679, 2023). "The results demonstrated that SERPINE2 protein expression was significantly upregulated in COAD and PAAD tumor tissues in a comparison with a normal one (p < 0.05)." (PMID 38274096, 2023). "Simultaneously, YTHDF2 exerts an inhibitory effect on HCC, inhibiting growth of tumor cells and vessels by processing interleukin 11 (IL11) mRNA and serpin family E member 2 (SERPINE2) mRNA." (PMID 34105069, 2021). "Our results indicate that YTHDF2 represses both tumor cells and tumor vasculature by processing IL11 and SERPINE2 mRNAs to decay." (PMID 31735169, 2019). "A cytokine array analysis was also carried out on CM from tumor samples, revealing a strong increase in secretion of the MMP inhibitor TIMP-1, in response to Ab11 treatment and serpinE2 KD." (PMID 27793045, 2016). "Additionally, previous studies have indicated that SERPINE2, as an extracellular secretory factor, can bind to EGFR receptors and influence the malignant transformation of tumor cells." (PMID 40463876, 2025). "Furthermore, down-regulation of YTHDF2 reduces degradation of tumor-promoting factors IL11 and SERPINE2 mRNA, thereby facilitating tumor development." (PMID 41446042, 2025). "Subgroup analysis indicated that the mRNA levels of Serpine2 were notably higher in metastatic patients than in non-metastatic patients, specifically within Fn-positive tumor tissues." (PMID 40642075, 2025). "Furthermore, the relationship between SERPINE gene expression and tumor stages was analyzed in selected cancers from different databases, where the results indicated that SERPINE1 and SERPINE2 expression were significantly increased in advanced-stage COAD." (PMID 38274096, 2023). "To investigate whether SERPINE2 promoted the tumor malignant biological behavior and metastasis in RCC, we validated the function of SERPINE2 in RCC by qRT-PCR." (PMID 36646679, 2023). "SERPINE2 was highly expressed in the tissues from patients with LN or other metastases (n = 89) as compared with that in the primary tumor tissues with no metastasis (n = 199) (p < 0.05)." (PMID 36646679, 2023). "YTHDF2 can also inhibit HCC tumor cells and related vessels by processing IL11 and SERPINE2 mRNAs." (PMID 34105069, 2021). "In addition, m6A modification can also regulate the expression of VEGFA through the miR-143-3P/VASH1 axis, as well as through the regulation of SERPINE2, IL11, and HDGF stability, thus affecting tumor angiogenesis." (PMID 33926508, 2021). "The study revealed that YTHDF2 inhibits HCC progression through m6A modification by decreasing the stability of interleukin 11 (IL11) and serpin family E member 2 (SERPINE2) mRNA, which are involved in tumor angiogenesis and inflammation activation respectively." (PMID 32733807, 2020). "Serpin peptidase inhibitor clade E member 2 (SERPINE2/protease nexin-1) and secretory leukocyte protease inhibitor (SLPI) are secreted serine protease inhibitors which are overexpressed in a number of cancers and involved in tumor formation." (PMID 28255192, 2017).
tumor (continued). "Following injection into mammary fat pads of SCID mice, primary tumor growth was not affected by serpinE2 KD, similar to what was seen with the 4T1 model." (PMID 27793045, 2016). "The effects of inhibiting serpinE2 in tumors are multifaceted: ERK signaling was lowered, CCL2 levels were decreased, a skewing of tumor-promoting M2-like macrophages towards the M1-like phenotype was observed, and the level of the protease inhibitor TIMP1 increased." (PMID 27793045, 2016). "Treatment with Ab11 had no impact on tumor outgrowth, which is similar to results from serpinE2 KD tumors, however, tumors from dovitinib-treated groups, with or without Ab11, were significantly smaller." (PMID 27793045, 2016). "Our molecular analysis of these nodules indicates that reduction of Serpine2/Pn-1 interferes primarily with tumor cell proliferation and malignant progression, but does not promote differentiation into specific neuronal or glial cell-types." (PMID 25901736, 2015). "None of the 15 known or supposed markers for CTC detection was considered for further investigations either due to detectable expression levels (ERBB2, ESR1, SERPINE1, SERPINE2 and FN1) in healthy controls or due to inadequate gene expression in the tumor cell lines." (PMID 21129172, 2010). "Notably, in comparison to Fn-negative patients, there was a significant upregulation of Serpine2 mRNA and protein expression in Fn-positive tumor samples." (PMID 40642075, 2025). "Knowing that Caki-1 originates from the human RCC metastatic tumor site, we performed Hi-C, ATAC-seq, combined with RNA-seq between Caki-1 and HK-2 to explore whether the chromatin spatial structures and epigenetic factors contributed to gene and function regulation in SERPINE2." (PMID 36646679, 2023). "As a transcription factor, LHX2 may transcriptionally regulate the expression of a group of tumor-related genes, SERPINE2 did not completely rescue the phenotype induced by LHX2 knockdown in ESCC, we speculate that there may be other gene mediating the roles of LHX2 in the malignant phenotypes." (PMID 36011368, 2022). "In our study, inhibition of SERPINE2 significantly decreased the BAP31-induced cell proliferation and colony formation of HCC cells and the phosphorylation of Erk1/2 and p38, suggesting that SERPINE2 may promote tumor cell proliferation through activation of the MAPK pathway." (PMID 33363167, 2020). "Moreover, we showed that tumor-derived, and not host-derived serpinE2 is essential for metastasis." (PMID 27793045, 2016). "Similar to the results obtained with MDA-MB435 serpinE2 KD cells, blocking serpinE2 with Ab11 did not affect MDA-MB435 tumor growth." (PMID 27793045, 2016). "However, how SERPINE2 mediates LHX2-promoting tumor growth and the metastasis of ESCC still remains unclear, and our study failed to clarify the clinical significance of LHX2 and SERPINE2 in ESCC." (PMID 36011368, 2022).